CCNB1 (cyclin B1)
Diseases named in the same sentence as CCNB1 in open-access papers (continued):
Sharing a sentence is not in itself a finding about the gene and the disease.
liver cancer (29 papers, 2012 to 2026). An epithelial or non-epithelial malignant neoplasm that arises from the liver. "Taken together, our results suggest TOP2A, RRM2, NEK2, CDK1, and CCNB1 as HCC-associated hub genes that can serve as potential prognostic biomarkers in liver cancer." (PMID 34681056, 2021). "Numerous studies have investigated the impact of CCNB1 on liver cancer, and the present research confirms its potential role in this malignancy." (PMID 39118438, 2024). "Studies have shown that high expression of CDK1, CCNB1, and CCNA2 is associated with reduced overall survival in patients with liver cancer." (PMID 35463358, 2022). "Costunolide upregulates Chk2 (Thr68), p-Cdc25c (Ser216), p-Cdk1 (Tyr15), and cyclin B1 in liver cancer (HA22T/VGH) cells." (PMID 35651747, 2022). "The results revealed DNA topoisomerase II alpha (TOP2A), ribonucleotide reductase regulatory subunit M2 (RRM2), never in mitosis-related kinase 2 (NEK2), cyclin-dependent kinase 1 (CDK1), and cyclin B1 (CCNB1) as the hub genes for liver cancer." (PMID 34681056, 2021). "Our results suggest the potential use of TOP2A, RRM2, NEK2, CDK1, and CCNB1 as prognostic biomarkers in liver cancer." (PMID 34681056, 2021). "Taken together, our results strongly indicated that liver cancer patients with an upregulated level of TOP2A, RRM2, NEK2, CDK1, and CCNB1 were associated with poor prognosis." (PMID 34681056, 2021). "Subsequent validation suggested TOP2A, RRM2, NEK2, CDK1, and CCNB1 as the prognostic biomarkers of liver cancer." (PMID 34681056, 2021). "As a support of this, we verified that in liver cancer, the expression of Let-7 and CYCLIN B1 mRNA is negatively correlated, in a similar manner, compared to NSTI versus CPI." (PMID 31354514, 2019). "Taken together, our studies showed that NV669 inhibits the proliferation of pancreatic and hepatic cancer cells through the regulation of G2/M phase transition via the cyclin B1-Cdk1 complex." (PMID 31803360, 2019). "As a mechanistic study to find the molecular mechanism of CCNB1 regulation based on its abnormally high expression in liver cancer, we also conducted bioinformatical analysis to identify the miR-144 was targeting CCNB1 by binding to its 3′ UTR." (PMID 30651720, 2019). "In this study, we explored liver cancer expression profiles from TCGA public databases and found the expression level of CCNB1 was abnormally elevated in hepatocarcinoma tissues." (PMID 30651720, 2019). "Accordingly, butyrate, as an inhibitor of histone deacetylation, inhibits the growth of liver cancer cells via down-regulation of cdc2 and cyclin E and cyclin B1 in oral cancer cells." (PMID 27893752, 2016). "Taken together, these results suggest that galangin may induce apoptosis in liver cancer cells by disrupting the cell cycle through its influence on cell cycle proteins such as CCNB1, CDK4, CDK1, and PLK1." (PMID 38816744, 2024). "The data presented indicate that Anln, Hmmr, Tpx2, Ccnb1, and Ccnb2 may be influenced by changes in miR-122 expression and potentially contribute to liver cancer development." (PMID 37566034, 2023). "Therefore, the expression levels of AURKA, BIRC5, CCNB1, CDK1, CDKN3 and TYMS served as diagnostic markers for liver cancer patients." (PMID 37393234, 2023). "Downregulation of MELK, MAD2L1, and CCNB1 can also inhibit cell cycle progression of liver cancer." (PMID 32420375, 2020). "Kaplan–Meier analysis showed that the survival time of patients with low expression of CCNB1 was significantly better than that of patients with high expression of CCNB1, suggesting that the expression of CCNB1 is closely related to the clinical prognosis of patients with liver cancer." (PMID 30651720, 2019). "Western blot indicated a dose-dependent reduction in the expression of cyclin B1, an important G2 checkpoint protein, in the two liver cancer cells, suggesting that PP-induced G2 phase cell cycle arrest might be mediated by the down-regulated expression of cyclin B1." (PMID 22470568, 2012).
liver cancer (continued). "Meanwhile, immunohistochemical results of AURKA, CCNB1, CDC20 and TOP2A were found through the HPA database, which also confirmed that there were significant differences between liver cancer tissues and normal adjacent tissues." (PMID 39537209, 2024). "These genes, including RRM2, CCNB1, EZH2, and HMMR, are intricately involved in regulating essential cellular pathways and signaling cascades that are critical in the pathogenesis of liver cancer." (PMID 39118438, 2024). "To study CCNB1 in HCC, we first analyzed mRNA expression in HCC tissues and normal liver tissues based on the liver cancer gene expression profiles in the TCGA database." (PMID 30651720, 2019). "Notably, and in agreement with what was observed in the mouse models of liver cancer, ANLN, HMMR, TPX2, CCNB1, and CCNB2 expressions were found to be significantly upregulated in TCGA-LIHC." (PMID 37566034, 2023). "The combination of CCNB1 and CDC20 high expression could predict the poor prognosis of liver cancer, similar to what we got in ACC." (PMID 35983531, 2022). "In addition to CCNB1, CDK1, CDC45, BUB1B, and CCNA2, we also identified five hub genes in Chinese liver cancer, namely AURKA, KIF11, TOP2A, TPX2, and HMMR, which play a crucial role in regulating the cell cycle." (PMID 34257537, 2021). "Cyclin B1 (CCNB1) mRNA levels were examined in non-tumor and liver cancer of The Cancer Genome Atlas (TCGA) cohort." (PMID 30651720, 2019). "In addition, GEPIA online analysis showed that ESR1, AR, CCNB1, CDK1, AKR1C3 and CCNA2 might become potential target genes for the survival and prognosis of PADP for the treatment of liver cancer." (PMID 35463358, 2022). "Interestingly, three of them (CCNB1, TOP2A, NEK2) were also identified as crucial genes in HCV-HCC, which might to some extent reflect the common transcriptome regulatory mechanisms in liver cancer induced by viral hepatitis." (PMID 33946043, 2021).
lung adenocarcinoma (27 papers, 2017 to 2025). A carcinoma that arises from the lung and is characterized by the presence of malignant glandular epithelial cells. "CCNB1 expression was associated with the infiltration of T helper cells, and this further correlated with poor prognosis for certain cancers, including renal clear cell carcinoma and lung adenocarcinoma." (PMID 37758792, 2023). "CPLX1 is one of several factors able to influence the activity of cyclin B1 (CCNB1), which is highly expressed in lung adenocarcinoma and associated with poor prognosis." (PMID 38797520, 2024). "Gene expression of CCNB1 correlated positively with poor prognosis of tumor patients, and these results were confirmed at the protein level using lung adenocarcinoma." (PMID 37758792, 2023). "Using lung adenocarcinoma data, we studied the potential upstream noncoding RNAs involved in the regulation of CCNB1 and validated the protein levels and prognostic value of CCNB1 for this disease site." (PMID 37758792, 2023). "Hsa-miR-181c-5p and hsa-miR-181d-5p were recognized as CCNB1 upstream regulatory microRNAs in lung adenocarcinoma." (PMID 37758792, 2023). "Based on the good performance of CCNB1 in multiple analyses of lung adenocarcinoma, we mainly explored the ceRNA regulatory mechanism of CCNB1 in lung adenocarcinoma." (PMID 37758792, 2023). "Subsequently, we identified a specific upstream noncoding RNA contributing to CCNB1 overexpression in lung adenocarcinoma through correlation analysis, expression analysis and survival analysis." (PMID 37758792, 2023). "We also found that cyclin B1 (CCNB1) is regulated by MYBL2 and FOXM1, and overexpression of CCNB1 is associated with poor survival of lung adenocarcinoma patients." (PMID 36291764, 2022). "We found that overexpression of these 8 genes (CENPA, FAM83D, KNSTRN, CDKN3, CCNB1, CDK1, and CCNA2) is significantly associated with poor survival of lung adenocarcinoma patients (p-value < 0.05)." (PMID 36291764, 2022). "Mechanistically, Gliclazide inhibited the proliferation of lung adenocarcinoma cells possibly by targeting CCNB1, CCNB1, CDK1 and AURKA to induce cell cycle arrest and apoptosis." (PMID 34249701, 2021). "The overexpression of CCNB1 was an independent factor for unfavorable disease-free survival and had an unfavorable prognosis in patients with lung adenocarcinoma." (PMID 31007608, 2019). "Silencing of FOXM1 expression by siRNA in A549 lung adenocarcinoma cells resulted in significant reduction in cell cycle-promoting cyclin A2 and cyclin B1 genes, as well as DNA replication and mitosis." (PMID 31681566, 2019). "The 10-gene biomarker panel also includes CCNB1, which is a key cell-cycle regulator and known prognostic predictor of lung adenocarcinoma." (PMID 28426704, 2017). "Finally, a comprehensive analysis of TCGA, GEPIA and Kaplan-Meier Plotter databases revealed that high mRNA expression of CCNB1, CDC25C, CENPM, and EXO1 was associated with poor survival in lung adenocarcinoma patients." (PMID 35646074, 2022). "LINC01667 can act as a sponge to regulate genes such as CCNB1, CEP55, MKI67, and TYMS, and ultimately affect the progression of lung adenocarcinoma." (PMID 34458133, 2021). "It is well known that CCNB1 is highly expressed in NSCLC and is a potential biomarker for both lung adenocarcinoma and lung squamous cell carcinoma, belonging to two subtypes of NSCLC." (PMID 33669233, 2021).
lung adenocarcinoma (continued). "The results indicated that dried apricot polyphenols (DAPs) could cause cell cycle arrest in the G0/G1 and G2/M phases by decreasing the cyclin D1, CDK4, cyclin B1, CDK1, and CDK6 levels in A549 human lung adenocarcinoma cells." (PMID 39796398, 2025).
esophageal cancer (22 papers, 2013 to 2025). A primary or metastatic malignant neoplasm involving the esophagus. "CCNB1 is involved in the pathogenesis of esophagus carcinoma, and the CCNB1 upregulation is associated with a poor prognosis in patients with ESCC34." (PMID 38519533, 2024). "Three hub targets were retrieved, including CENPF, CCNA2 (cyclin A), and CCNB1 (cyclin B1), which were highly expressed in esophageal cancer and associated with prognosis." (PMID 35484963, 2022). "The positive/high expression of cyclin B1 had an obvious association with 3-year OS in patients with esophageal cancer according to the pooled results (OR 0.21, 95% CI 0.12–0.37; P < 0.00001)." (PMID 29221213, 2017). "This blockade led to reduced expression of IL-19-regulated genes such as TGF-β, Matrix Metalloproteinase-1 (MMP-1), CXCR4, and Cyclin B (CCNB1), highlighting the therapeutic potential of IL-19 inhibition in esophageal cancer." (PMID 40806452, 2025). "In conclusion, based on DEGs and key modules related to esophageal cancer, CCNB1 was identified as the hub gene, which offered novel insights into the development and treatment of esophageal cancer." (PMID 33632229, 2021). "Based on DEGs and key modules related to esophageal cancer, CCNB1 was identified as the hub gene, which offered novel insights into the development and treatment of esophageal cancer." (PMID 33632229, 2021). "It is worth noting that the CDK1‐binding compound cyclin B1 (CCNB1) is overexpressed in the tumorigenesis of esophageal cancer." (PMID 34586751, 2021). "It revealed that esophageal cancer patients with positive/high expression of cyclin B1 had worse prognosis." (PMID 29221213, 2017). "However, there have been few reports on the direct correlation between CCNB1 and esophageal cancer, and our research has made important explorations in this area." (PMID 33632229, 2021). "Cyclin B1 was also related to the proliferation of esophageal cancer cells." (PMID 24130695, 2013). "Moreover, the high expression of CCNB1 shows positive association with unfavorable outcomes for non-small-cell lung, breast, gastric, and esophageal cancers." (PMID 36712863, 2022). "Moreover, esophageal cancer patients with higher expression of CCNB1 showed a worse prognosis." (PMID 33632229, 2021). "Similarly, for location of tumor the cyclin B1 overexpression in loose bound mucosa is rapidly proliferating in VC than COSCC when compared to bound down mucosa and this is in concurrence with various other sites like tongue and esophagus carcinoma." (PMID 23722120, 2013).
esophageal squamous cell carcinoma (19 papers, 2012 to 2024). Esophageal squamous cell carcinoma (ESCC) is a type of esophageal carcinoma (EC) that can affect any part of the esophagus, but is usually located in the upper or middle third. "Elevated CCNB1 expression is associated with poor prognosis in patients with squamous cell carcinomas of the esophagus, larynx, lung, and tongue." (PMID 39795587, 2024). "Moreover, overexpression of CCNB1 is implicated in metastasis, likely by promoting epithelial-mesenchymal transition in colorectal tumors and esophageal squamous cell carcinoma cells." (PMID 39795587, 2024). "It has also been found that HSP90α is associated with the prognosis of human esophageal squamous cell carcinoma, and may be involved in the regulation of cyclin B1 expression." (PMID 36158677, 2022). "But the interesting thing is that our former study showed a G2/M arrest with cyclin B1 down-regulation when the STAT3 was knockdown in TE1 cell line which is also an esophageal squamous cell carcinoma." (PMID 29636641, 2018). "Taken together, our findings suggested that amentoflavone could be a potential cell cycle inhibitor targeting cyclin B1, and is therefore expected to serve as a great therapeutic agent for treating esophageal squamous cell carcinoma." (PMID 35484963, 2022). "The siRNA knockdown approach showed significantly reduced cell proliferation, colony formation and invasion when an endogenous CCNB1 was disrupted in oesophageal squamous cell carcinoma (ESCC) cells." (PMID 36418517, 2023). "Cyclin B1, encoded by the CCNB1 gene, is regulated by H2B ubiquitination at its promoter by the E2 enzyme radiation sensitive 6 (RAD6) in esophageal squamous cell carcinoma (ESCC), affecting ESCC cell proliferation." (PMID 39048965, 2024).
osteosarcoma (18 papers, 2009 to 2023). A usually aggressive malignant bone-forming mesenchymal neoplasm, predominantly affecting adolescents and young adults. "This article investigated the effect of miR-449a /CCNB1 axis on osteosarcoma through using bioinformatics analysis and “wet” experiments." (PMID 36545680, 2022). "Several drugs were reported to inhibit cell proliferation or induce cell cycle arrest and apoptosis in human osteosarcoma by downregulating CCNB1 and CDK1." (PMID 32665038, 2020). "Overexpression of CCNB1 can facilitate the growth rate of osteosarcoma cells and increase their sensitivity to paclitaxel." (PMID 32665038, 2020). "This treatment induced the accumulation of cyclin B1 and DNA condensation indicating the treated osteosarcoma cells were arrested in mitotic phase." (PMID 30142914, 2018). "In this report, we observed that the pretreatment with JNK inhibitor prevented the accumulation of cyclin B1 in coronarin D-exposed osteosarcoma cells." (PMID 30142914, 2018). "Blocking JNK activation with JNK inhibitor prevented the accumulation of cyclin B1 and rounded morphology, inhibited mitotic progression, and arrested cells in the 4 N state in coronarin D-treated osteosarcoma cells." (PMID 30142914, 2018). "Currently miRNA has been considered as a potential anticancer drug, in a recent study, researchers investigated the effect of miR-449a/CCNB1 axis on osteosarcoma through bioinformatics analysis and in vitro cellular assays, demonstrating that investigated miR-449a can inhibit osteosarcoma growth." (PMID 37007086, 2023). "MiRNA-449a is down-regulated in osteosarcoma and suppresses cell proliferation by targeting CCNB1." (PMID 36545680, 2022). "In addition, naringenin induced cell cycle arrest in osteosarcoma cells by inhibiting cyclin B1 and cyclin-dependent kinase 1 expression and upregulating p21 expression." (PMID 35056691, 2022). "Whether EEF1D directly or indirectly affects CyclinD1/Cdk4 or Cyclin B1/Cdk1 activity in osteosarcomas remains to be investigated." (PMID 29510727, 2018). "Pretreatment with JNK inhibitor blocked the accumulation of cyclin B1 and DNA condensation, resulting the accumulation of tetraploid cells in coronarin D-treated osteosarcoma HOS cells, indicating JNK inactivation blocked the mitotic entry and arrested cells in the 4 N state." (PMID 30142914, 2018). "Another most interesting observation in our study is that a few of the hub genes of Rb tumors including CDK1, CDK2, CCNB1, HDAC1 and UNC5D are reported to play a key role in the pathogenesis of osteosarcoma, the most common secondary cancer in Rb patients." (PMID 35359459, 2022). "In this report, we showed that the treatment with coronarin D resulted in the accumulation of cyclin B1, DNA condensation, and arrested cells in mitotic phase following JNK activation in osteosarcoma cells." (PMID 30142914, 2018). "But there was still no clear understanding of the mechanism by which miR-449a /CCNB1 worked in osteosarcoma." (PMID 36545680, 2022). "The data showed that the protein level of phospho-cdc2, cdc2, and Cdc25C were decreased in treated both cell lines, but Cyclin B1 protein levels had no apparent change in HOS cells and was decreased in MG-63 cells, indicating Licochalcone A induces G2/M phase arrest of osteosarcoma cell lines." (PMID 31269698, 2019).